TFAP2A (transcription factor AP-2 alpha)
Description:
Sequence-specific DNA-binding protein that interacts with inducible viral and cellular enhancer elements to regulate transcription of selected genes. AP-2 factors bind to the consensus sequence 5'-GCCNNNGGC-3' and activate genes involved in a large spectrum of important biological functions including proper eye, face, body wall, limb and neural tube development. They can also suppress a number of genes including MCAM/MUC18 and C/EBP alpha. Is involved in the negative regulation of Wnt canonical signaling, and is a transcriptional repressor of MYC. AP-2-alpha is the only AP-2 protein required for early morphogenesis of the lens vesicle. Together with the CITED2 coactivator, stimulates the PITX2 P1 promoter transcription activation. Associates with chromatin to the PITX2 P1 promoter region.
Synonyms: AP-2; AP2TF; TFAP2; AP-2alpha; BOFS
Tractability: Small molecule: a structure with a bound ligand is known. PROTAC: UniProt records ubiquitination sites on it; ubiquitination databases record sites on it.
Gene: Protein-coding gene on chromosome 6 (10,393,186 to 10,419,659, reverse strand). Ensembl gene ENSG00000137203.
Subcellular location: Nucleus
Subcellular location (Human Protein Atlas): Nucleoplasm
Pathways (Reactome):
Gene expression (Transcription): Activation of the TFAP2 (AP-2) family of transcription factors; Negative regulation of activity of TFAP2 (AP-2) family transcription factors; TFAP2 (AP-2) family regulates transcription of cell cycle factors; TFAP2 (AP-2) family regulates transcription of growth factors and their receptors; TFAP2 (AP-2) family regulates transcription of other transcription factors; TFAP2A acts as a transcriptional repressor during retinoic acid induced cell differentiation; Transcriptional regulation by the AP-2 (TFAP2) family of transcription factors
Developmental Biology: Developmental Lineage of Mammary Stem Cells; Regulation of MITF-M-dependent genes involved in pigmentation; Specification of the neural plate border
Cell-Cell communication: Positive Regulation of CDH1 Gene Transcription
Metabolism of proteins: SUMOylation of transcription factors
Gene Ontology:
Molecular function: DNA binding; DNA-binding transcription activator activity, RNA polymerase II-specific; DNA-binding transcription factor activity, RNA polymerase II-specific; DNA-binding transcription repressor activity, RNA polymerase II-specific; identical protein binding; protein binding; RNA polymerase II cis-regulatory region sequence-specific DNA binding; sequence-specific DNA binding; sequence-specific double-stranded DNA binding; transcription cis-regulatory region binding; chromatin binding; RNA polymerase II transcription regulatory region sequence-specific DNA binding; DNA-binding transcription factor activity
Biological process: cellular response to iron ion; inner ear morphogenesis; kidney development; negative regulation of apoptotic process; negative regulation of cell population proliferation; negative regulation of DNA-templated transcription; negative regulation of reactive oxygen species metabolic process; negative regulation of transcription by RNA polymerase II; positive regulation of bone mineralization; positive regulation of DNA-templated transcription; positive regulation of neuron apoptotic process; positive regulation of tooth mineralization; positive regulation of transcription by RNA polymerase II; regulation of cell differentiation; retina layer formation; roof of mouth development; sensory perception of sound; bone morphogenesis; embryonic cranial skeleton morphogenesis; embryonic forelimb morphogenesis; eyelid development in camera-type eye; nervous system development; oculomotor nerve formation; optic cup structural organization; optic vesicle morphogenesis; and 5 more
Cellular component: nucleoplasm; nucleus; chromatin
Genetic constraint (gnomAD): Loss-of-function variants: 6 observed, 35.45 expected, observed/expected ratio (o/e) 0.17, 90% interval 0.092 to 0.33. The upper end of that interval is the gene's LOEUF score, 0.33, which puts it in group 1 of 6, group 1 being the genes least tolerant of losing a copy. Missense variants: 394 observed, 553.9 expected, observed/expected ratio (o/e) 0.71, 90% interval 0.65 to 0.77. Synonymous variants: 237 observed, 243.61 expected, observed/expected ratio (o/e) 0.97, 90% interval 0.87 to 1.08.
Homologues: Orthologues: chimpanzee TFAP2A (100% identical), pig TFAP2A (99% identical), rat Tfap2a (99% identical), guinea pig TFAP2A (98% identical), macaque TFAP2A (97% identical), dog TFAP2A (95% identical), mouse Tfap2a (95% identical), tropical clawed frog tfap2a (89% identical), zebrafish tfap2a (86% identical), rabbit TFAP2A (84% identical), Drosophila melanogaster TfAP-2 (49% identical), Caenorhabditis elegans aptf-1 (33% identical), and 3 more. Paralogues in human: TFAP2B (75% identical), TFAP2C (65% identical), TFAP2E (62% identical), TFAP2D (52% identical).
Diseases named in the same sentence as TFAP2A in open-access papers:
TFAP2A is named in the same sentence as 162 diseases in open-access papers, as found by Europe PMC text mining. Sharing a sentence is not in itself a finding about the gene and the disease. The quoted sentences say what the papers report.
breast carcinoma (43 papers, 2003 to 2025). "While TFAP2A, a member of the AP-2 transcription factor family, has been implicated in maintaining the basal phenotype of breast cancer, its precise regulatory role in TNBC remains undefined." (PMID 38890750, 2024). "TFAP2A expression was found to be less organized in breast cancer compared to normal mammary gland and it is associated with HER2/ErbB-2 and ERα expression." (PMID 28412966, 2017). "Reduced expression levels of TFAP2A have been associated with increased metastatic capability in breast cancer with poor prognosis reported in gastric adenocarcinoma patients." (PMID 26697505, 2016). "Heterogeneous nuclear ribonucleoprotein C could promote collagen fiber alignment and immune escape in breast cancer by activating vir like m6A methyltransferase associated-mediated TFAP2A/discoidin domain receptor tyrosine kinase 1 axis." (PMID 40813717, 2025). "Furthermore, we analyzed association between TFAP2A expression and prognosis of breast cancer using survival analysis." (PMID 38890750, 2024). "The high mutation rate of TFAP2A may lead to the increased expression of DJ-1 to promote the progression of breast cancer." (PMID 38125697, 2023). "TFAP2A has been found to be associated with a variety of tumors and is highly expressed in a variety of tumor cells including glioma, gastric cancer, bile duct cancer, breast cancer, and colorectal cancer, regulating tumor proliferation and apoptosis." (PMID 35494004, 2022). "The Ku70/Ku80 complex was previously also shown to interact with TFAP2A in breast cancer cell lines, in which recruitment of Ku70 together with TFAP2A was needed for the transcriptional activation of the ERBB2 proximal promoter." (PMID 39994865, 2025). "Although, TFAP2A is highly expressed in luminal breast cancer, SUMOylation endowed to TFAP2A hinders its transcriptional activation on luminal-type associated genes." (PMID 38890750, 2024). "Through a comprehensive bioinformatics analysis utilizing multiple databases, TFAP2A emerged as a particularly intriguing candidate due to its crucial role in maintaining the basal-like phenotype of breast cancer." (PMID 38890750, 2024). "Selective silencing of TFAP2A significantly impeded the proliferation and migration of TNBC cells, with elevated TFAP2A expression observed in breast cancer tissues." (PMID 38890750, 2024). "To specifically explore the potential role of TFAP2A in TNBC, we investigated the TFAP2A protein levels in different subtypes of breast cancer." (PMID 38890750, 2024). "Of note, in luminal breast cancer subtypes, TFAP2A has been found to exhibit reduced transcriptional activity on luminal genes due to its high sumoylation level." (PMID 38890750, 2024). "Consistently, comparing with corresponding normal tissues, TFAP2A mRNA and protein levels are upregulated in breast cancer." (PMID 38890750, 2024). "The expression levels of TFAP2A and TFAP2C are reduced post-translationally during TNFα-induced cell apoptosis, during which TFAP2A is cleaved by caspase 6 and degraded by the proteasome in the breast cancer cells." (PMID 37291585, 2023). "Transcription factor-activating enhancer binding protein 2 alpha (TFAP2A) is upregulated as an oncogene in many cancers, including breast cancer." (PMID 37204526, 2023). "Many studies have shown that TFAP2A overexpression promotes the proliferation, migration, and invasion of breast cancer cells." (PMID 38125697, 2023). "The decreased expression of TFAP2A resulting from hypermethylation leads to chemoresistance to adriamycin and cisplatin in breast cancer." (PMID 37291585, 2023). "Collectively, these results demonstrated that the transcription factor TFAP2A is overexpressed in breast cancer cells and is necessary for the transcriptional overexpression of UBE2T." (PMID 36338541, 2022).
breast carcinoma (continued). "Regarding AP-2 transcription factors in the mammary gland and breast cancer, most studies have focused on TFAP2A/AP-2α and TFAP2C/AP-2γ." (PMID 34117603, 2021). "For example, relevant studies indicated that TFAP2A promotes the proliferation, migration and invasion of breast cancer cells, and Shi et.al revealed that TFAP2A promotes nasopharyngeal carcinoma cell proliferation and inhibits apoptosis." (PMID 33493131, 2021). "In total, seven TFs (HOXC11, FOXA1, SPDEF, SOX12, HOXC10, GATA3 and TFAP2A) were annotated to the breast cancer samples." (PMID 34712617, 2021). "Previously, miR-876-5p was reported to inhibit the progression of breast cancer by targeting TFAP2A." (PMID 32883232, 2020). "TFAP2A was elevated in breast cancer tissue and cell lines and more highly expressed in tamoxifen resistant tumor tissues and cell lines." (PMID 29439714, 2018). "Using the GOBO online tool we found that TFAP2A expression is reduced in the basal B breast cancer cell lines, which have a higher expression of the mesenchymal markers compared to the basal A type cell lines." (PMID 28412966, 2017). "Intriguingly, very little is known about SETD5 in breast cancer progression and metastasis, while TFAP2A is involved in both sporadic and hereditary breast cancer." (PMID 28086829, 2017). "To gain further insight into the relationship between TFAP2A expression and activity, we examined the mRNA expression data that was previously generated from human breast cancer cell lines." (PMID 28412966, 2017). "SUMO-conjugated TFAP2A was highly expressed in the basal breast cancer cell line IOWA-1T, whereas only the SUMO-unconjugated form of TFAP2A was detected in the luminal cell line MCF-7." (PMID 29383121, 2017). "This study suggested SUMOylation of the TFAP2A transcription factor is critical to maintain the basal breast cancer phenotype, providing therapeutic potential for basal breast cancer." (PMID 25860128, 2015). "For example, SUMOylation of transcription factor AP-2 alpha (TFAP2A) has been reported to maintain the basal breast cancer phenotype, and inhibition of SUMOylation induces a basal to luminal transition through deregulation of TFAP2A transcriptional targets." (PMID 25522242, 2014). "Methylated breast cancer cell lines treated with 5-aza-2'-deoxycytidine induced reexpression of TFAP2A, resulted in apoptosis induction, increased chemosensitivity, decreased colony formation and loss of tumorigenesis upon chemotherapy." (PMID 20184741, 2010). "In breast cancer cells it has been demonstrated that expression of TFAP2A increased the chemosensitivity of cancer cells by sensitizing cells to undergo apoptosis upon chemotherapy." (PMID 20184741, 2010). "Binding of TFAP2A in promoter regions of the same hypoxia‐dependent genes could be also shown in breast carcinoma MCF7 cells, suggesting that binding of TFAP2A to HIF‐regulated promoters is not a cell type‐specific event." (PMID 39994865, 2025). "HER2 positive breast cancer has a highest expression of TFAP2A, which is consistent with the reports that TFAP2A could regulate HER2 expression." (PMID 38890750, 2024). "As an important transcription factor in maintaining basal-like subtype breast cancer, whether and how TFAP2A modulates EMT in TNBC is poorly understood." (PMID 38890750, 2024). "In the present study, we specifically investigate the role of TFAP2A in TNBC, and found TFAP2A expression is negatively associated with overall survival of TNBC patients; whereas in Luminal B subtype breast cancer, high expression of TFAP2A indicates a favorable outcome." (PMID 38890750, 2024).
breast carcinoma (continued). "During breast cancer evolution, several CpG sites within the TFAP2A gene are hypermethylated; in particular, an approximately 300bp area at the 3' end of exon 1 can be obviously correlated with transcriptional inactivation and further distinguish tumors from normal breast tissue." (PMID 37291585, 2023). "It is worth nothing that TFAP2A was also found in the second real case, which suggested that TFAP2A may play a crucial role in the poor prognosis of patients with breast carcinoma." (PMID 37468850, 2023). "The transcription factor TFAP2A regulates UBE2T expression in breast cancer cells, and previous study has shown that TFAP2A regulates the expression of several genes that promote cancer growth and contribute to determining anticancer therapy resistance and sensitivity." (PMID 36338541, 2022). "SUMOylation of TFAP2A is necessary to maintain basal breast cancer phenotypes." (PMID 33968766, 2021). "Another report showed that TFAP2A mediates SUMO pathway inhibition in breast cancer, indicating that TFAP2A may act as an upstream regulator of the SUMO pathway to regulate global SUMO modification in tumor cells and thus influence the cellular phenotype." (PMID 33968766, 2021). "Another study showed that SUMOylation of TFAP2A is necessary to maintain basal breast cancer phenotypes, suggesting that there may be a mutual regulatory relationship between TFAP2A and the SUMO pathway." (PMID 33968766, 2021). "To test this hypothesis in ATC, we screened a panel of ATC cell lines for expression of TFAP2A compared to breast cancer cells as a control." (PMID 29383121, 2017). "TFAP2A expression was found to be less organized in breast cancer compared to normal mammary gland." (PMID 28412966, 2017). "TFAP2A encodes AP-2α, recently shown to be essential for RA action, has previously been reported to stimulate CRABP2 expression in mammary epithelial cells and breast cancer cells." (PMID 26142905, 2015). "TFAP2A, a sequence specific DNA binding transcription factor has been demonstrated to be frequently methylated in large B-cell lymphoma, renal cell carcinoma and breast cancer." (PMID 20184741, 2010). "Recent evidence suggests that TFAP2A may promote the progression of breast cancer." (PMID 38890750, 2024). "TFAP2A, also known as AP-2-α, is a transcription factor regulating the differentiation and proliferation of breast, the upregulation of which inhibits cell cycle, promotes apoptosis, and suppresses invasion in breast cancer via the regulation of various miRNAs." (PMID 33336077, 2021). "In breast cancer, alteration of SUMOylation on TFAP2A and TFAP2C demonstrates potential transformation between luminal and basal breast cancer phenotypes and concordant gene signatures." (PMID 37291585, 2023). "However, the specific mechanism of TFAP2A in breast cancer remains unclear." (PMID 38125697, 2023). "Our results showed that TFAP2A knockdown reduced UBE2T expression at the mRNA and protein levels in breast cancer cells." (PMID 36338541, 2022). "We demonstrate that the transcription factor AP-2 alpha (TFAP2A) is necessary for the overexpression of UBE2T in breast cancer cells, and UBE2T inhibition suppresses breast cancer tumor growth in cell culture and in mice." (PMID 36338541, 2022). "The TFAP2A and TFAP2G transcription factors are involved in regulation of proliferation, differentiation as well as apoptosis in normal breast epithelium and breast cancer." (PMID 35494004, 2022). "UBE2T expression is regulated by transcription factor AP-2 alpha (TFAP2A), and UBE2T inhibition suppresses breast cancer tumor growth." (PMID 36338541, 2022). "However, one of the TFs annotated in our study, TFAP2A, has not been extensively studied in breast cancer, and may be a new critical TF associated with the disease." (PMID 34712617, 2021). "For breast cancer, we present an interaction between SPRY2 and C0L10A1 and for kidney one between TFAP2A and SGPP1." (PMID 32859146, 2020).
breast carcinoma (continued). "Conversely, TFAP2A and TFAP2B correlated with good overall and disease-free survival in breast cancer patients." (PMID 29439714, 2018). "In breast cancer, TFAP2A functioned as a tumor suppressor; conversely, TFAP2C played an oncogenic role in the development and progression of breast cancer." (PMID 29439714, 2018). "Our study sheds a new light on the role of TFAP2A in processes that involve EMT, including breast cancer, and it contributes to a deeper understanding of the molecular and cellular mechanism of cancer development and metastasis." (PMID 28412966, 2017). "Mechanically, TFAP2A and TFAP2C are capable of binding the ERBB2 promoter, and in collaboration with other transcription factors, such as Ku protein and Yin Yang 1, they significantly promote ERBB2 expression in breast cancer cells." (PMID 37291585, 2023). "The lncRNA MAFG-AS1 acts as a sponge for miR-3169 and TFAP2A is a target of miR-3169, and knocking down MAFG-AS1 could lead to inactivation of the JAK2/ STAT pathway, thereby inhibiting breast cancer progression." (PMID 37204526, 2023). "TFAP2A knockdown also inhibited the abilities of breast cancer cells to grow in an anchorage-independent manner in soft-agar assays, mimicking the growth inhibitory phenotype observed with UBE2T inhibition in breast cancer cells." (PMID 36338541, 2022). "Interestingly, among all the breast cancer subtypes, we observed a negative correlation between TFAP2A expression and patients’ overall survival time in basal-like breast cancer, whereas a positive correlation was observed in luminal B breast cancer." (PMID 38890750, 2024). "Additionally, the discovery of TFAP2A as a transcription activator of SNAI1 enhances our understanding of the complex molecular pathways involved in TNBC progression, emphasizing TFAP2A as a key regulator in this aggressive subtype of breast cancer." (PMID 38890750, 2024). "We found that TFAP2A is one of the factors that contribute most significantly to mRNA-level expression changes that take place during embryonic stem cell (ESC) differentiation to mesoderm or to NC cells, during normal mammary gland development, and most importantly, in breast cancer models." (PMID 28412966, 2017). "In contrast to TFAP2A, TFAP2C has been shown to be over-expressed, rather than lost in breast cancer cell lines and primary tumors." (PMID 24023917, 2013).